INSR (insulin receptor)
Diseases named in the same sentence as INSR in open-access papers (continued):
Sharing a sentence is not in itself a finding about the gene and the disease.
Insulin resistance (continued). "The kidney, functioning as a “target organ for insulin receptor,” exhibits insulin resistance when its sensitivity and responsiveness to endogenous or exogenous insulin diminish." (PMID 41323824, 2025). "This cascade ultimately disrupts insulin receptor signaling pathways in adipocytes, resulting in systemic insulin resistance." (PMID 40078991, 2025). "Animal trial suggested that deleting TNF-α protects from the obesity-related decrease in insulin receptor signaling in fat tissues and muscles, being a central factor contributing to insulin resistance in diet-induced obesity." (PMID 40565251, 2025). "BEOV was able to normalize glucose intake in the brains of AD-affected mice and regulate insulin receptor (InsR) activity, a vital intermediary in Aβ-induced insulin resistance." (PMID 40572513, 2025). "Overexpression of SOCS inhibits the insulin signaling system by blocking the binding of insulin receptor substrates (IR) to the insulin receptor (IR), leading to insulin resistance." (PMID 39968090, 2025). "Mechanistic studies have illuminated its role in phosphorylating IRS1 (insulin receptor substrate), converting it into an inhibitor of insulin receptor signaling, leading to insulin resistance in myeloid cells." (PMID 40868889, 2025). "The resulting chronic inflammation activates serine kinases, including JNK and IKK, which phosphorylate the insulin receptor and impair its normal binding to insulin, culminating in insulin resistance." (PMID 41357185, 2025). "These bacterial taxa can exert anti-inflammatory effects through the production of SCFAs, which reduce the generation of IKK and subsequently inhibit its interaction with the insulin receptor, thereby alleviating insulin resistance." (PMID 41357185, 2025). "In particular, TNF exacerbates insulin resistance by inhibiting insulin receptor phosphorylation and GLUT4 translocation." (PMID 41266905, 2025). "Insulin resistance in the background of PCOS partially depends on increased serine phosphorylation of an insulin receptor that influences insulin signaling pathways." (PMID 39866289, 2025). "In in vitro studies and in animal models, TNF-alpha actives c-JUN N-terminal kinase (JNK) 1 and IκB kinase (IKK), which in turn inhibit insulin receptor activation, which can lead to insulin resistance." (PMID 40218888, 2025). "When insulin receptor signaling in adipose tissue is impaired, leading to insulin resistance, the balance of lipolysis is disrupted." (PMID 40933566, 2025). "CD248 has been shown to directly interact with the insulin receptor, blocking binding to insulin and promoting insulin resistance in mice." (PMID 40229590, 2025). "The HFD induces brain insulin resistance by reducing the tyrosine phosphorylation of the insulin receptor and increasing the serine phosphorylation of insulin receptor substrate 1, which can disrupt the proteins involved in the insulin signaling pathway." (PMID 40149843, 2025). "On the metabolic front, these compounds enhance insulin receptor sensitivity, mitigate insulin resistance, suppress inflammation-driven UPS activation, and downregulate Atrogin-1 and MuRF-1." (PMID 41514616, 2025). "Chronic mTORC1 activation can disrupt insulin signaling by hyperactivating S6K1, which phosphorylates insulin receptor substrates on serine residues, impairing insulin signal transmission and promoting insulin resistance." (PMID 39796608, 2025). "The compound S961, a specific insulin receptor antagonist, was used to elicit insulin resistance in control and glycine- or β-alanine–treated mice." (PMID 40260914, 2025). "Research shows that patients with Parkinson’s disease have high insulin resistance and decreased levels of insulin receptor mRNA in SNpc in comparison with healthy controls." (PMID 39859258, 2025). "In obesity, their expression increases, and they impede the insulin receptor’s tyrosine kinase activity, compete for receptor binding, or degrade IRS proteins, causing insulin resistance." (PMID 40141412, 2025).
Insulin resistance (continued). "Saturated fatty acids (FAs), by affecting the cell wall structure and insulin receptor activity, act in favour of the initiation of glucose metabolism disorders and are potentially responsible for insulin resistance." (PMID 40218956, 2025). "In cardiomyocytes exhibiting insulin resistance, insulin receptor signaling is partly complemented by insulin-like growth factor 1 receptor signaling." (PMID 40141412, 2025). "For instance, exosomes from the muscle and fat cells contain miR-1 and miR-133, which target IRS-1 and INSR, inhibiting insulin signaling and leading to insulin resistance." (PMID 41438998, 2025). "Viscosol improved insulin resistance by significantly up regulating INSR, IRS1, PI3K, andGLUT4 expression at both transcriptional and translational levels." (PMID 40173145, 2025). "Excessive gestational weight gain exacerbates insulin resistance through hyperleptinemia, which downregulates insulin receptor expression via JAK/STAT signaling." (PMID 40076938, 2025). "Altogether, our findings present in vivo evidence supporting TRIM32’s role in the negative regulation of liver insulin receptor signaling in mice with HFD-induced insulin resistance." (PMID 39747658, 2025). "Utilizing a holistic approach encompassing in vitro and in vivo experiments, we identified the E3 ubiquitin ligase TRIM32 as a critical regulator of INSR degradation during the development of HFD-induced insulin-resistance in mice." (PMID 39747658, 2025). "The pro-inflammatory cytokines released in both conditions, such as TNF-α, IL-6, and IL-1β, impair insulin receptor signaling, leading to insulin resistance." (PMID 41007787, 2025). "TNF-α plays a pivotal role in hepatic insulin resistance by activating serine/threonine kinases that phosphorylate and inactivate insulin receptor substrates, thereby blocking insulin receptor signaling cascades." (PMID 40951429, 2025). "Thirdly, lipoprotein remnants in RC can interfere with intracellular insulin signaling pathways, potentially binding to insulin receptors or disrupting the phosphorylation and activation of insulin receptor substrates, thereby exacerbating insulin resistance." (PMID 39508748, 2025). "Aging neurons are accompanied by an increase in insulin resistance and a decrease in sensitivity to insulin receptors, such as IR and IGF‐IR, resulting in inefficient glucose utilization." (PMID 41395450, 2025). "On a cellular level, insulin resistance is defined as the insufficient strength of insulin signaling from the insulin receptor (InsR) downstream to the final substrates, compromising numerous metabolic aspects of cellular function." (PMID 40277891, 2025). "Hyperinsulinemia can also drive additional cellular insulin resistance by decreasing insulin receptor (Insr) levels as well as through multiple post-receptor mechanisms." (PMID 40105689, 2025). "Chronic inflammation, in turn, exacerbates insulin resistance by disrupting insulin receptor signaling and promoting the release of pro-inflammatory cytokines." (PMID 40729004, 2025). "According to reports, CrPi3 improves β-cell sensitivity, insulin receptor number, and insulin internalization to reduce insulin resistance." (PMID 38276548, 2024). "At the molecular level, insulin resistance is characterized by inefficient insulin signal transduction in pathways from the insulin receptor (INSR) to the final targets of insulin." (PMID 39770980, 2024). "TNF-α is thought to reduce insulin signaling by decreasing the phosphorylation of the insulin receptor substrate-1 (IRS-1) Tyr632 and Akt Ser473, which are downstream effectors of the insulin receptor, thereby resulting in insulin resistance." (PMID 39200235, 2024). "DM1-related changes in insulin signaling have been reported in ∼30 clinical studies, and insulin resistance is a key phenotype due to, at least partially, the aberrant regulation of insulin receptor (INSR) splicing." (PMID 38760841, 2024).
Insulin resistance (continued). "In T2D, metabolic syndrome and insulin resistance lead to dysfunctional insulin receptor signaling, which in turn affects downstream Akt signaling." (PMID 38581667, 2024). "In the state of insulin resistance, there are aberrations in the insulin receptor signaling pathway, specifically a reduction in tyrosine phosphorylation of IRS1 and inhibition of the PI3K/Akt signaling pathway." (PMID 38449844, 2024). "Mutations in the INSR gene have been associated with various inherited insulin resistance syndromes, such as leprechaunism, Rabson-Mendenhall syndrome (RMS), and type A insulin resistance." (PMID 38957655, 2024). "PTP1B is known to be important in insulin receptor desensitization, increased PTP1B expression is associated with insulin resistance and PTP1B is being evaluated as a therapeutic for patients with T2D." (PMID 38199575, 2024). "With the increase in pro-inflammatory cytokine secretion by adipose cells, the expression of insulin receptor substrate and glucose transporter 4 is decreased, inducing insulin resistance." (PMID 39705291, 2024). "During aging, or the development of obesity and diabetes, the whole-body insulin response generally shifts to the right, and the right-shift is regarded as a sign of insulin resistance and is construed as a defect of insulin receptor function." (PMID 39617270, 2024). "A similar process occurs in insulin resistance, where interventions improve insulin signaling, reduce hormone levels, and consequently lower blood glucose levels due to enhanced insulin receptor function." (PMID 39458475, 2024). "Insulin resistance is characteristic of T2DM and it is caused mostly by impairment in the insulin receptor (IR) signal transduction pathway." (PMID 39595931, 2024). "Inflammation is significant in diabetes mellitus; an inordinate increase of inflammatory factors hinders insulin receptor signaling and leads to insulin resistance." (PMID 38398510, 2024). "On the contrary, with dysregulation of GPX3 potentially impacting insulin receptor functionality and contributing to insulin resistance." (PMID 38927092, 2024). "TNFα is crucial in insulin resistance, as it interferes with insulin receptor signalling by phosphorylating ISR1/2, inhibiting Akt, and therefore diminishing the translocation of GLUT4 to the plasma membrane." (PMID 38953241, 2024). "Together with diminished pulsatility of insulin and downregulated insulin receptor number, chronic hyperinsulinemia increases DNL and causes hepatic insulin resistance." (PMID 39640841, 2024). "This inflammation interferes with normal insulin receptor function, worsening insulin resistance and contributing to reduced bone mineral density (BMD)." (PMID 39339002, 2024). "For instance, the binding between HDAC2 and insulin receptor substrate-1 (IRS-1) can impair insulin receptor-mediated tyrosine phosphorylation, leading to insulin resistance." (PMID 39596347, 2024). "IL-6 disrupts insulin signaling by activating pathways that phosphorylate insulin receptor substrates (IRS), leading to reduced insulin receptor activity and insulin resistance, a hallmark of T2DM." (PMID 39857603, 2024). "SAF-189s was developed on the basis of the structure of ceritinib with a lower IC50 of 0.8 nM, which would induce insulin resistance owing to its inhibitory effects on INSR." (PMID 39081957, 2024). "First described by Rabson and Mendenhall in 1956, RMS is a rare form of congenital severe insulin resistance (c.SIR) caused by biallelic, loss-of-function variants of the insulin receptor (INSR; 19p13.3-p13.2)." (PMID 38978877, 2024). "Based on our results and the referenced literature, we propose that increased chain splitting of endogenous insulin prior to insulin receptor activation—throughout the body or locally—is a direct mechanism of in vivo insulin resistance." (PMID 40604313, 2024).
Insulin resistance (continued). "In conclusion, our findings indicate that insulin induces insulin resistance in human DPSCs, resulting in impairments in proximal insulin signaling events (INSR, IGF1R, IRS1, and PI3K) while maintaining the activity of distal pathway components (AKT and mTOR)." (PMID 39075596, 2024). "It further triggers apoptosis of adipocytes and insulin resistance through insulin receptor suppression, oxidation and oxidative phosphoryliosis in adipocytes’ mitochondria." (PMID 39062927, 2024). "Their synergistic action is evident as vitamin D enhances the expression of insulin receptor genes, improving cell sensitivity to insulin, which helps in improving insulin resistance." (PMID 39183985, 2024). "Studies have supported that that overexpression of PTP1B negatively affects protein tyrosine kinases, and in consequence, induces leptin and insulin resistance because insulin is unable to bind with INSR and finally leads to T2DM." (PMID 39759127, 2024). "Previous studies have found that selective decrease in arcuate nucleus insulin receptor levels, and increase in POMC can cause weight gain, increased adiposity, and rapid onset of hepatic insulin resistance 70,71." (PMID 39005353, 2024). "The selective INSR antagonist, S961, is also useful for exploring the impact of acute insulin resistance on BIR under various conditions." (PMID 37611907, 2024). "Observations performed on animal models of diabetes and insulin resistance revealed the decreased expression of INSR and phosphorylated INSR in renal epithelial cells." (PMID 38397072, 2024). "ADAM17 has been shown to cleave the ectodomain of the insulin receptor, which can result in insulin resistance." (PMID 38963109, 2024). "Vitamin D has additional receptors in adipocytes, muscle, and hepatocytes reducing insulin resistance by enhancing insulin receptor expression and insulin responsiveness for glucose transport, and regulating calcium metabolism." (PMID 38459212, 2024). "More precisely, CRP induces insulin resistance by activating the MAPK signaling pathways or interfering with the IRS/PI3K/AKT signaling pathway (insulin receptor substrate/phosphatidylinositol 3 kinase/AKT)." (PMID 39430749, 2024). "The digestive enzymes trigger a hallmark of aging, as detected by the breakdown of collagen, and they generate signatures for insulin resistance in the form of hyperglycemia and extracellular insulin receptor cleavage." (PMID 39418235, 2024). "GH excess disrupts normal insulin receptor phosphorylation and its signaling pathways, leading to insulin resistance." (PMID 39337013, 2024). "In many cancers, dysregulation of insulin receptors (INSR) is a common occurrence, with insulin resistance in metabolic tissues often leading to downregulation of INSR expression." (PMID 38272982, 2024). "Our investigation revealed elevated insulin levels in both female OVX/HFHSD mice and diabetic human subjects, concomitant with decreased INSR expression in both groups, indicating a reciprocal relationship between insulin resistance and INSR levels." (PMID 39337631, 2024). "Concerning the molecular mechanisms underpinning the link between vitamin D and insulin resistance, it has been demonstrated that vitamin D enhances insulin receptor expression in muscle, liver, and adipose tissue, thereby improving insulin sensitivity." (PMID 39201651, 2024). "The mechanisms behind insulin resistance involve altered insulin receptor signaling and glucose transporter expression, with obesity exacerbating these issues through increased fatty acid levels and inflammatory markers." (PMID 38770513, 2024). "Insulin receptor (INSR) mutations, first described in 1988, are the most common cause of monogenic insulin resistance and hyperglycaemia." (PMID 38461278, 2024). "The regulation of INSR expression or post-transcriptional events has also been proposed as mechanisms leading to insulin resistance." (PMID 37611907, 2024).
Insulin resistance (continued). "More than 90% of primary insulin resistance is attributed to multiple genetic mutations such as those affecting the glucose transporter type 4 (GLUT4), glucokinase, and insulin receptor substrate gene." (PMID 40302954, 2024). "To definitively answer this question in an animal model of human insulin resistance before the onset of dysglycaemia we crossed mice haploinsufficient for the insulin receptor (IR+/−) with atherosclerosis-prone Apolipoprotein E holoinsufficient mice (ApoE−/−)." (PMID 39401163, 2024). "In another study focusing on insulin resistance, HepG2 liver-derived cells were used to investigate the cleavage of the insulin receptor (IR), highlighting the significant role of exosomes." (PMID 38473976, 2024). "We also analyzed the levels and the phosphorylation of the IRS1 protein, an important player in controlling insulin receptor signaling and in promoting insulin resistance." (PMID 37298533, 2023). "TNF-α can stimulate serine phosphorylation of the insulin receptor, which leads to insulin resistance." (PMID 36788534, 2023). "In particular miR-15b was suggested to contribute to development of future insulin resistance by downregulation of the insulin receptor and upregulation of PI3KR1, leading to impaired insulin signaling." (PMID 38288471, 2023). "Development of compounds that intervene at PPIs occurring downstream of the insulin receptor would be beneficial in understanding insulin resistance." (PMID 38202781, 2023). "Previous study indicated that CYP2J3 overexpression improved insulin resistance in rats treated with fructose and in db/db diabetic mice, improving insulin resistance by activating insulin receptor signaling and adiponectin-mediated AMPK signaling pathways." (PMID 37370090, 2023). "Variation within the insulin receptor and autoantibodies to the receptor can also result in insulin resistance, requiring further work from the receptor perspective." (PMID 36830626, 2023). "Most women with PCOS have systemic insulin resistance from perturbed insulin receptor/post-receptor signaling, altered adipokine secretion and/or abnormal steroid metabolism, in combination with preferential abdominal fat accumulation worsened by obesity." (PMID 37834765, 2023). "In this group, a mutation in the region of the Grb14 gene has been suggested to be what drives insulin resistance, given that Grb14 is an effector of insulin signaling and directly inhibits insulin receptor catalytic activity in vitro." (PMID 37217826, 2023). "A tyrosine phosphorylation reduction accompanies adipose insulin resistance on the insulin receptor." (PMID 36976988, 2023). "Increased hepatic lipid accumulation induces hepatic insulin resistance through PKC-mediated phosphorylation of the insulin receptor at Thr 1160, thereby impairing glucose homeostasis and promoting the development of T2DM." (PMID 37960324, 2023). "In conclusion, we identify that ZFYVE28 is involved in insulin signaling and mediates insulin resistance by promoting phosphorylated insulin receptor degradation." (PMID 37884540, 2023). "A reduction of insulin receptor expression and impairment of insulin signaling characterizes insulin resistance." (PMID 36902167, 2023). "Inflammation or other stress stimuli block the PI3K signaling pathway downstream of the insulin receptor through the activation of several serine/threonine kinases, contributing to insulin resistance in adipocytes." (PMID 36875140, 2023). "Brain insulin resistance is characterized by a reduced response to insulin signaling downstream of the insulin receptor (IR) in the brain, consequently leading to metabolic alteration, neurodegeneration, and cognitive impairment." (PMID 36875654, 2023). "TNF-α promotes the activity of a series of proteins such as IKK that act directly on the substrate (IRS) of the insulin receptor, leading to the development of insulin resistance in muscle cells." (PMID 36918975, 2023).